HP (haptoglobin)
Diseases named in the same sentence as HP in open-access papers (continued):
Sharing a sentence is not in itself a finding about the gene and the disease.
diabetes (68 papers, 2007 to 2026). "High haptoglobin expression (positive cells ≥ 30.8%) in skin lesions is associated with higher HS severity, active smoking, more pain, and the comorbidities of diabetes mellitus and arterial hypertension in HS patients." (PMID 40430166, 2025). "The facilitation of Hb clearance by haptoglobin is greatly dependent on Hp gene polymorphisms and their structuraldifferences which make it a susceptibility marker in diabetes patients." (PMID 37654824, 2022). "Haptoglobin is an acute-phase protein used as predicting diagnostic biomarker both in humans (i.e., diabetes, ovarian cancer, some neurological and cardiovascular disorders) and in animals (e.g., bovine mastitis)." (PMID 31910856, 2020). "Along with the prominent difference in the antioxidative properties of proteins coded by the different HP genotypes, Hp has been reported to be associated with many inflammatory diseases, including cardiovascular disease, autoimmune disorders and diabetes." (PMID 32794371, 2020). "Over the past several decades, haptoglobin (HP) polymorphism has been linked to complications arising from diabetes." (PMID 31504048, 2019). "Our data indicate that elevations in IL-1β and IL-12 at the initial stages of KRV+pIC treatment, coupled with sustained elevations of haptoglobin, are associated with progression to diabetes in BBDR rats." (PMID 24147110, 2013). "Recently, many studies have revealed the association between haptoglobin phenotypes and various infections and diseases such as diabetes, cancer, and cardiovascular diseases." (PMID 23555085, 2013). "HP, which was downregulated and is associated with diabetic nephropathy and type 2 diabetes mellitus, appeared in the UPB database." (PMID 22536212, 2012). "For example, haptoglobin (Hp) genotype is an independent risk factor for vascular complications in diabetes." (PMID 22690338, 2012). "Many known risk factors of diabetes such as C-reactive protein, serum amyloid A and haptoglobin were over-represented in diabetic serum, in agreement with the observations by traditional approaches based on the analysis of individual proteins." (PMID 18795103, 2008). "Furthermore, the analysis shows that high haptoglobin expression is associated with an increased risk of metabolic comorbidities such as diabetes mellitus and arterial hypertension." (PMID 40430166, 2025). "Because of its role in the removal of oxidative species from the circulation, both high and low levels of haptoglobin are indicative of a variety of disorders with low levels associated with autoimmunity and increased levels occurring in inflammation, diabetes, and cardiovascular disease." (PMID 37513613, 2023). "Subgroup analyses show that vitamin E may be promising in reducing the rate of cardiovascular events among diabetes patients with haptoglobin 2-2 genotype who are at increased risk of cardiovascular events." (PMID 30621135, 2019). "In support of APP glycosylation as a risk factor for disease, synthesis and glycosylation of AGP, haptoglobin, and transferrin are associated with a number of chronic diseases such as pancreatitis, rheumatoid arthritis, diabetes, and inflammatory lung conditions." (PMID 28642810, 2017). "The results are in accordance with a study from the Malmö Preventive Project, which reported nonsignificant relationships for ceruloplasmin, alpha-1-antitrypsin, haptoglobin and orosomucoid and incident diabetes after adjustments for fasting glucose and other risk factors." (PMID 27581604, 2016). "The RCTs in diabetes patients that retrospectively analyzed the data for the effect of vitamin in E found that administration of vitamin E lowered the risk of cardiovascular disease events by 34% and cardiovascular-related mortality by 53% among patients with the haptoglobin 2-2 genotype." (PMID 30621135, 2019).
diabetes (continued). "Haptoglobin levels have been repeatedly associated with a variety of inflammation-linked infectious and non-infectious diseases, including malaria, tuberculosis, human immunodeficiency virus, hepatitis C, diabetes, carotid atherosclerosis, and acute myocardial infarction." (PMID 22403646, 2012). "Importantly, a number of recent studies implicate the absolute amount and quality of the HP gene product as an independent risk factor for a multitude of diseases including: diabetes; atherosclerosis; poor clinical outcome following myocardial infarction; and percutaneous coronary interventions." (PMID 20016837, 2009). "For the LRS analysis, the independent variables were BMI, systolic blood pressure, diabetes duration, HbA1c, triglycerides, ferritin, haptoglobin, direct bilirubin, creatinine, and AMMi (parameters used to calculate the score were not included)." (PMID 41010909, 2025). "This study investigates the relationship between insulin–glucose homeostasis, diabetes mellitus and the haptoglobin concentration in HS patients." (PMID 40217596, 2025). "HS patients with elevated haptoglobin levels had an increased risk of developing metabolic complications (grade III obesity and/or diabetes mellitus)." (PMID 40022488, 2025). "Haptoglobin phenotype was measured in 4542 samples from the Action for Health in Diabetes (Look AHEAD) study." (PMID 38402400, 2024). "Circulating zonulin, a pre-haptoglobin molecule that has, up to now, been only regarded as the inactive precursor of haptoglobin, is set as a marker of intestinal permeability in autoimmune diseases and diabetes." (PMID 39062940, 2024). "Roguin and colleagues found that the Haptoglobin (HP) genotype was a significant independent predictor of MACE in patients with diabetes." (PMID 33171725, 2020). "We studied the impact of Vit-E supplementation on vascular function in diabetes individuals stratified by haptoglobin genotype in Singapore." (PMID 32341356, 2020). "We conducted a randomised controlled trial (RCT) to study the impact of Vit-E supplementation on inflammation, oxidative stress, vascular function in diabetes individuals stratified by haptoglobin genotype." (PMID 32341356, 2020). "Recently, haptoglobin genotype has been identified as a pertinent factor in diabetes, sickle cell, and cardiovascular disease, with the Hp 2-2 genotype contributing to increased complications." (PMID 29904350, 2018). "The haptoglobin (Hp) genotype (1-1 and 2-2) is a major determinant of nephropathy progression in diabetes mellitus patients." (PMID 30250850, 2018). "Of the five acute-phase proteins, subjects in the fourth compared to the first quartile of orosomucoid, haptoglobin and CRP, respectively, had significantly higher risk of incidence of diabetes in the first model." (PMID 27581604, 2016). "The aim of this prospective study is to investigate the relationship between plasma levels of five acute-phase proteins (CRP, ceruloplasmin, alpha-1-antitrypsin, orosomucoid, and haptoglobin) at baseline and incidence of diabetes in a population-based cohort." (PMID 27581604, 2016). "This is in accordance with findings from a case-control study by McMillan, which showed increased levels of haptoglobin, orosomucoid, and CRP in association with diabetes and glucose intolerance." (PMID 27581604, 2016). "In conclusion, this study demonstrated that there are associations between orosomucoid, haptoglobin, and CRP and the risk of incident diabetes." (PMID 27581604, 2016). "The study demonstrated that there are associations between orosomucoid, haptoglobin and CRP and the risk of incidence of diabetes." (PMID 27581604, 2016). "Expression of transcription factors (ANGPTL2, HP, LEP, SAA1, SAA2), genes related to inflammation (SAA1, LEP), diabetes (IGFBP5) and cancer risk (SAA2) were also elevated upon exposure to 5 nM PhIP.." (PMID 27547236, 2016).
diabetes (continued). "Patients with diabetes also had higher sICAM-1, sVCAM-1, haptoglobin, adiponectin, triglycerides, total cholesterol, LDL, ALT, and 25-hydroxyvitamin D compared to non-diabetic controls." (PMID 27459718, 2016). "The present study revealed significant associations between the acute-phase proteins orosomucoid, haptoglobin, and CRP and increased incidence of diabetes when adjusted for several potential confounders." (PMID 27581604, 2016). "Orosomucoid, haptoglobin, and CRP showed a significant increased risk of diabetes after adjustment for potential confounders." (PMID 27581604, 2016). "Patients with diabetes had higher levels of cytoadhesive molecules (sICAM-1 and sVCAM-1, p<0.001), adiponectin (p<0.001), and haptoglobin (p = 0.023)." (PMID 27459718, 2016). "In conclusion, significant biomarkers of inflammation (TNFα, IL-6, hsCRP, and haptoglobin) and endothelial dysfunction (sICAM-1 and sVCAM-1) are present in young patients with diabetes, obesity, and dyslipidemia." (PMID 27459718, 2016). "Third, doses of salicylate that prevented diabetes also blocked or reduced elevations in these inflammatory cytokines and haptoglobin." (PMID 24147110, 2013). "Haptoglobin is considered as another antioxidant defense in diabetes, because this plasma protein binds free hemoglobin resulting in the inhibition of iron-induced oxidative damage." (PMID 23742649, 2013). "Haptoglobin genotypes were determined in 1208 European Americans (EA) from 473 Diabetes Heart Study (DHS) families via PCR." (PMID 23399657, 2013). "In all of these cases, lower levels of functional haptoglobin increase the likelihood of developing diabetes and cardiovascular disease." (PMID 20016837, 2009). "Haptoglobin genotype has been shown to regulate reverse cholesterol transport in diabetes in vitro and in vivo." (PMID 19627602, 2009). "Studies also showed that haptoglobin and C-reactive protein were increased significantly in both diabetes and glucose intolerance." (PMID 18795103, 2008). "Haptoglobin types may affect the interpretation of the HbA1c levels in the estimation of glucose controls in diabetes patients, since haptoglobin is involved in hemoglobin turnover." (PMID 23555085, 2013). "Another study also reported that the elevation of vitamin D-binding protein, haptoglobin, and α-2 microglobulin was noted in the diabetes mellitus (DM) dialysate." (PMID 23781506, 2013). "The selected target genes (HP and Cu/Zn SOD) have a defensive role against diabetes as their increased expression helps to prevent diabetes mellitus by decreasing oxidative stress." (PMID 37145997, 2023). "In the first category, we identified significant correlation between HP/GH and various forms of hypertension and cardiological diseases, as well as between GD and such traits as diabetes mellitus (DM) (rg=1±0.28, p-value=1.14×10−8) and soft tissue disorders (rg=0.57±0.21, p-value=9.95×10−8)." (PMID 36553520, 2022). "Diabetes is known to downregulate CD163, the hemoglobin:haptoglobin (Hb:haptoglobin) scavenger receptor." (PMID 32879134, 2020). "We further discovered marked changes in prediabetes/diabetes-related proteins (AACT/SERPINA3, AAT/SERPINA1, ApoA-I, HP, RBP4, TTR, and ZAG)." (PMID 31504048, 2019). "Relative expression of HP (P < 0.01) A2M (P < 0.01), NCOA4 (P < 0.001) and HAMP (P < 0.01, P < 0.05) gene was significantly downregulated in PCOS female with complaint of kidney disease compared to PCOS females with diabetes, BP and both with diabetes and BP." (PMID 40057801, 2025). "Differentially regulated genes not overlapping with ERCB data also reflected diabetes-associated changes, such as extracellular matrix (ANGPTL4, TNN, DPT, COL9A2) or gestational diabetes (LAT2, HP, CXCL10, CD86, CD68, REN, SLC2A3, VCAM1)." (PMID 33923831, 2021). "Glycated α1-antitrypsin and haptoglobin levels were further determined in blood obtained from living diabetics and non-diabetic control individuals as well as in blood obtained from diabetic cadavers." (PMID 26088843, 2015).
diabetes (continued). "In terms of categorical variables, the gender distribution was similar between the two groups (χ2 = 0.06, P = 0.804), but the prevalence of diabetes was significantly higher in the HP-positive group compared to the HP-negative group (4.73% and 3.34%, respectively; χ2 = 7.76, P = 0.005)." (PMID 41293740, 2025). "It is necessary to optimize the dynamic monitoring indicators of HbA1c, combine genetic profiles, haptoglobin phenotypes for example and select more suitable hypoglycemic drugs to establish more appropriate glucose-controlling guideline for patients with CHD at different stage of diabetes." (PMID 37349787, 2023). "In patients with non-alcoholic fatty liver disease (NAFLD) with or without type 2 diabetes mellitus (T2DM), alpha-2 macroglobulin (A2M), apolipoprotein A1 (ApoA1), and haptoglobin are associated with the risk of liver fibrosis, inflammation (NASH), and COVID-19." (PMID 35327501, 2022). "Similar to our study, no relation was found for alpha-1-antitrypsin and haptoglobin with diabetes." (PMID 27581604, 2016).
mastitis (50 papers, 2008 to 2026). Inflammation of breast tissue during lactation or postpartum due to an obstructed duct or infection. "Using serum and milk HP and amyloid A as a diagnostic marker of subclinical mastitis yielded a sensitivity of more than 90% and a specificity ranging from 56.66 to 100% depending on the cut-off used." (PMID 39237955, 2024). "The PCR detected mRNA encoding haptoglobin in somatic cells of goat milk that were tested positive for mastitis by CMT test." (PMID 33665459, 2021). "Haptoglobin (acute phase protein) is a diagnostic biomarker widely used for evaluation of bovine mastitis." (PMID 33509059, 2021). "The study described the development of a haptoglobin-based diagnostic tool for mastitis in Ettawa crossbreed goats." (PMID 33665459, 2021). "Haptoglobin is a major acute phase protein in bovines and reportedly increases in serum and milk whey during mastitis, highlighting its potential as a diagnostic biomarker." (PMID 29056737, 2016). "We hypothesized that during mastitis, haptoglobin is secreted by somatic cells of goat milk and, and haptoglobin is a potential marker for the development of early diagnostic tool of mastitis in goats." (PMID 33665459, 2021). "Haptoglobin could be a suitable marker for the development of diagnostic test of subclinical mastitis in goats." (PMID 33665459, 2021). "The aim of the study was to determine the expressions of SAA3, HP, and CP genes in MECs and CLECs during chronic subclinical mastitis caused by CoPS and CoNS vs. bacteria-free udder samples to compare the immune response of both tissues to staphylococcal infection." (PMID 32867772, 2020). "Although the low between-animal variance and repeatability for haptoglobin found in the present study renders it an unlikely biomarker for genetic selection, its significant association with mastitis identifies it as a potentially useful predictor of disease at the phenotypic level." (PMID 23776543, 2013). "Levels of haptoglobin in both serum and milk have been shown to be increased in dairy cows with both experimentally-induced or naturally-occurring cases of mastitis, increasing rapidly (within 1–2 days) following experimental intra-mammary infection with mastitis-causing pathogens." (PMID 23776543, 2013). "For this study, cows exhibiting no clinical signs such as udder inflammation or milk clots or elevated haptoglobin levels were selected for SL analysis in the mastitis group." (PMID 41527118, 2026). "This study investigated the effects of inflammation (plasma haptoglobin concentration), ketosis, and mastitis on plasma SL profiles in Holstein cows sampled seven days postpartum." (PMID 41527118, 2026). "Further, an online sensing system enabling an automated California Mastitis Test (CMT) in milk has been developed, as well as a biosensor for the detection of mastitis based on acute-phase proteins (haptoglobin)." (PMID 40077447, 2025). "As with naturally occurring mastitis, the main APPs in focus were serum and milk HP and amyloid A. However, albumin was also studied." (PMID 39237955, 2024). "The major acute phase proteins in cattle are serum or milk amyloid A and HP, and the majority of literature reports oncases of clinical and subclinical mastitis." (PMID 39237955, 2024). "Significant increases in serum and milk amyloid A and HP are seen in subclinical mastitis, and the level corresponds to the number of udder quarters affected." (PMID 39237955, 2024). "Protein S100-A9, Protein S100-A8, Chitinase-3-like protein 1, Haptoglobin, Integrin beta-2, and Chloride intracellular channel protein 1 were more abundant in milk-derived EVs for clinical mastitis." (PMID 36611779, 2023). "Haptoglobin and inter-alpha-trypsin inhibitor heavy chain H4 were acute phase proteins reported in mastitis." (PMID 35479637, 2022). "Both haptoglobin and lactoferrin are acute phase proteins which are well-established biomarkers of clinical mastitis, having direct bactericidal activity against E. coli." (PMID 36009735, 2022).